GSDME (gasdermin E)
Diseases named in the same sentence as GSDME in open-access papers (continued):
Sharing a sentence is not in itself a finding about the gene and the disease.
tumor (continued). "GSDME is a newly recognized executor of pyroptosis and is usually silenced in various cancers as a putative tumor suppressor due to promoter hypermethylation." (PMID 37085908, 2023). "Yang and colleagues discovered that after PTX treatment, the caspase-3/GSDME pathway was activated to disrupt cell membranes and induce tumor cells pyroptosis." (PMID 38104141, 2023). "In mice with GSDME‐expressing tumors, knocking out GSDME increases tumor development, whereas ectopic expression inhibits tumor development." (PMID 37752941, 2023). "In summary, metal‐based nanomaterials are able to induce tumor cell pyroptosis through caspase‐1‐dependent classical pathways or GSDME‐dependent non‐classical pathways by disrupting tumor cell ion homeostasis and redox homeostasis in tumor cells." (PMID 37933288, 2023). "Consistent with the results in ESCC cell lines, rMV-Hu191 treatment induced GSDME cleavage in the xenograft tumor tissues." (PMID 37202386, 2023). "These in vivo results are consistent with those obtained in vitro and confirm that GSDME modulates tumor growth in HCC cells." (PMID 37149620, 2023). "In this review, we systematically summarize the latest research regarding the molecular mechanisms of pyroptosis and discuss the role of GSDME-mediated pyroptosis in anti-tumor immunity and its potential applications in cancer treatment." (PMID 38104141, 2023). "The activation of GSDME and caspase-3 through cleavage by Granzyme B leads to pyroptosis of tumor cells by NK cells, CD8+ killer lymphocytes, and chimeric antibody receptor T cells." (PMID 37077542, 2023). "When GSDME is highly expressed, chemotherapeutic agents induce tumor cell death through caspase-3-dependent pyroptosis." (PMID 37283803, 2023). "In mice, the upregulation of GSDME can enhance the phagocytosis of macrophages and increase the number and function of tumour-infiltrating natural killer cells and CD8 + T lymphocytes." (PMID 36600313, 2023). "Increased expression of GSDME leads to more active tumor-infiltrating natural killer and CD8+ T lymphocytes, as well as increased phagocytosis of tumor cells by tumor-associated macrophages." (PMID 37077542, 2023). "We observe that ORFV treatment can induce GSDME-mediated tumor cell pyroptosis both in vitro and in vivo." (PMID 36641456, 2023). "Here we show that ORFV and its recombinant therapeutic derivatives are able to trigger tumor cell pyroptosis via Gasdermin E (GSDME)." (PMID 36641456, 2023). "Very recently, however, it was also observed that GSDME gene methylation varied according to cancer type between tumor tissues and normal cells." (PMID 38104141, 2023). "For example, in breast cancer, GSDME acts as a tumor suppressor molecule and promotes tumor cell pyroptosis, enhances the phagocytic ability of macrophages, and increases infiltration by CD8 + T and natural killer cells, thereby promoting antitumor immunity." (PMID 37138146, 2023). "Overall, due to the fact that GSDME is typically methylated in tumor cells and expressed in most normal tissues, GSDME-mediated pyroptosis is a biological process responsible for the toxicity and side effects of certain chemotherapeutic medications." (PMID 38104141, 2023). "It was reported that several chemotherapeutic agents can induce pyroptosis in tumor cells via the caspase-3/GSDME pathway." (PMID 36823153, 2023). "Mechanistically, NK and CD8 T cytotoxic lymphocytes deliver granzyme B (GzmB) into GSDME-expressing tumor cells, where GzmB cuts GSDME to induce pyroptosis." (PMID 36742298, 2023). "When GSDME is highly expressed in tumor cells, active caspase-3 cleaves GSDME, and the N-terminal domain lodges itself within the cell membrane to punch holes, resulting in cell swelling, rupture, and death." (PMID 36827109, 2023). "For instance, PRGs, including NLRP3, Gasdermin D (GSDMD), Caspase 1 (CASP1), and Gasdermin E (GSDME), are highly associated with oncogenesis as well as tumor progression." (PMID 37149620, 2023).
tumor (continued). "NLRP6 and GSDME showed elevated methylation levels in tumor samples, while GSDMC showed the opposite characteristics." (PMID 35651286, 2023). "In OSCC, tumours with high expression of GSDME increased the number of infiltrating CD8 + T cells, granzyme B, and M1 phenotypic macrophages." (PMID 36600313, 2023). "Despite the benefits of pyroptotic induction in tumor therapy, GSDME is usually silent in most tumor cells but highly expressed in normal cells, and inappropriate activation of pyroptosis in normal tissues causes tissue damage." (PMID 37460805, 2023). "The recovery of GSDME expression in tumor cells is helpful to enhance the function of immune cells to inhibit tumor growth." (PMID 37153795, 2023). "After administering MCPP to tumor cells and followed by laser irradiation, MCPP selectively triggered GSDME-dependent tumor cell pyroptosis and improved immune checkpoint blockade efficiency." (PMID 38104141, 2023). "Under the challenge of ORFV, depletion of GSDME blocked pyroptosis, antitumor immunity, and tumor response." (PMID 36641456, 2023). "Due to its exceptional expression and methylation properties in various cancers, GSDME is a promising gene candidate for future investigation as a tumor detection biomarker." (PMID 38104141, 2023). "A pivotal study performed decitabine treatment for 6 days to increase GSDME mRNA level for accumulating enough GSDME in GSDME-low tumor cells." (PMID 36641456, 2023). "Many studies have reported that the expression of GSDME in tumors is suppressed by methylation and functions as a tumor suppressor in various tumors." (PMID 37085908, 2023). "We discovered that an ORFV-based therapeutic strategy can trigger GSDME-mediated tumor cell pyroptosis." (PMID 36641456, 2023). "As a tumor suppressor, GSDME has been demonstrated to inhibit cancer cell proliferation, migration, and differentiation." (PMID 36867605, 2023). "Granzyme B has been shown to be involved in tumor suppression by activating gasdermin E, which is involved in cellular pyroptosis, and is also known to play an important role in tumor immunity." (PMID 37298408, 2023). "Collectively, GSDME-mediated pyroptosis exhibits promise in augmenting anti-PD-1 treatment effectiveness and involves in tumor progression." (PMID 38104141, 2023). "After two rounds of ORFV treatment, the GSDME level was increased and cleaved in tumor tissues as expected." (PMID 36641456, 2023). "This underscores that GSDME’s tumor-suppressive function of GSDME is mediated through pyroptosis-induced activation of antitumor immunity." (PMID 38066523, 2023). "According to a recent study, oncolytic vesicular stomatitis virus (VSV) activates GSDME-mediated pyroptosis to induce tumor cell pyroptosis." (PMID 38104141, 2023). "Recently, the role of GSDME has attracted more and more attention, and many studies showed its excellent anti-tumor effects." (PMID 37658132, 2023). "Knockdown of GSDME dampened VSV-mediated tumor-antagonizing effects and reduced the ability of VSV to stimulate antitumor immune responses." (PMID 38283351, 2023). "Our results revealed that CC-115 suppresses tumor growth by inducing GSDME-mediated pyroptosis through the Akt/Bax-mitochondrial intrinsic pathway, indicating CC-115 as a promising therapeutic agent for LUAD." (PMID 37283803, 2023). "GSDME can enhance the phagocytosis of TAMs and the number and function of tumor lymphocytes, activating caspase-independent pyroptosis in target cells to inhibit tumors and enhance anti-tumor immunity." (PMID 37313458, 2023). "Lastly, GSDME was found to be overexpressed in tumor tissue from HNSCC patients, highlighting the relevance of this strategy." (PMID 35120582, 2022). "We found that GSDME, caspase‐3, and caspase‐8 were more highly expressed in tumor tissues than in adjacent normal tissues." (PMID 34553845, 2022). "In fact, chemotherapy and targeted agents also exert their anti-tumor activity through GSDME-induced pyroptosis." (PMID 36605187, 2022).
tumor (continued). "GSDME is considered a tumor suppressor, and its presence is negatively correlated with tumor viability." (PMID 35480866, 2022). "The epigenetic inactivation of GSDME in breast, colorectal, gastric and other cancers supported the view that GSDME is a tumor suppressor." (PMID 35462927, 2022). "Not surprisingly, the high expressions of GSDMA, GSDMC, GSDMD and GSDME were observed correlated with low tumor purity." (PMID 35164740, 2022). "Growing evidence has demonstrated that GSDME can act as a tumor suppressor, and an increased GSDME expression in tumors can improve its antitumor efficacy." (PMID 36612023, 2022). "GSDME, an inflammation-related protein possessing pore formatting capacity, induces cell swelling and fracture, showing its anti-tumor potential." (PMID 35541900, 2022). "Active caspase-3 drives pyroptosis of GSDME-positive tumour cells and release of alarmins that activate caspase-1 and GSDMD in neighbouring macrophages, finally resulting in macrophage-driven release of pro-inflammatory cytokines and CRS." (PMID 35455985, 2022). "GZMB induces GSDME-dependent pyroptosis in tumor targets both directly by cleaving GSDME and indirectly by activating caspase-3." (PMID 35673561, 2022). "For further verification, WB was performed on protein extracts from tumor tissues, and the results showed that the tumors treated with myricetin expressed cleaved-GSDME proteins." (PMID 36091790, 2022). "In the circulating tfRFP-B16 tumor cells, elevated reactive oxygen species (ROS) induced slight caspase-3 activation, a probable key factor in the cleavage of gasdermin E (GSDME) proteins and punching of holes in the tumor cell membrane." (PMID 36438480, 2022). "In a 2020 study, researchers found that CAT-T cells activate caspase-3/gasdermin E by activating granzyme B in tumor cells, thereby inducing tumor cell pyroptosis." (PMID 36038533, 2022). "In breast cancer, DRD2 promotes M1 polarization of macrophages and triggers GSDME-executed pyroptosis that regulates the tumor microenvironment and inhibits tumor malignant progression." (PMID 35958626, 2022). "GSDME expression suppresses tumor growth by enhancing the functionality of tumor-infiltrating natural-killer (NK) and CD8+ T lymphocytes." (PMID 36189269, 2022). "GSDME-expressing tumours increase the phagocytosis ability of macrophages and the numbers and functions of NK cells and CD8 + T lymphocytes." (PMID 35896522, 2022). "Consistently with our results, GSDME overexpression in tumor tissue has also been reported in different cancer types, which contrasts with the assumption that GSDME is silenced in tumors given its tumor suppressor role." (PMID 35120582, 2022). "GSDME, a tumor suppressor, has tremendous potential as a tumor biomarker, mediating inflammatory death of tumor cells and activating immune responses in favor of anti-tumor therapy." (PMID 35462927, 2022). "This form of proinflammatory cell death can be induced by the cleavage of gasdermin E and B by granzyme B and A, respectively, which are delivered into tumor cells via the action of perforin." (PMID 35503659, 2022). "Based on the tumor inhibition property of GSDME and the prevalence of methylation in cancer, several studies have shown that GSDME methylation is a valuable molecular biomarker in cancer." (PMID 35462927, 2022). "The use of low-dose decitabine, a methyltransferase inhibitor, can increase GSDME expression and inhibit tumor growth." (PMID 35480866, 2022). "Separate studies published the same year discovered that CD8+ T cells and NK cells both induce pyroptosis in tumor cells via granzyme B (an enzyme capable of cleaving GSDME)." (PMID 35677632, 2022). "GSDME has recently been considered a tumor suppressor that promotes tumor cell death by inducing pyroptosis." (PMID 35480866, 2022). "Another member of the Gasdermin family, GSDME, induces pyroptosis in a caspase-3-dependent manner and acts as a tumor suppressor in stomach cancer." (PMID 36262473, 2022).
tumor (continued). "Cleavage of gasdermin E by granzyme B is a potent mechanism by which cytotoxic lymphocytes can kill cancer cells and control tumour growth." (PMID 35401556, 2022). "Latest studies reported that GSDMB and GSDME in tumor cells are proteolyzed by granzymes of killer lymphocytes to trigger pyroptosis." (PMID 36323669, 2022). "In CAC, activation of GSDME causes pyroptosis and the release of HMGB1 inducing tumor cell proliferation and proliferating cell nuclear antigen (PCNA) expression through the ERK1/2 pathway and further promoting the development of CAC." (PMID 35411030, 2022). "Our study demonstrated that GA treatment induced the generation of GSDME-N fragments by cleaving GSDME-FL, which confirmed that pyroptosis was involved in GA-mediated tumor suppression in vivo." (PMID 36428598, 2022). "GSDME is silenced in various tumour cell types due to high methylation of the GSDME promoter region." (PMID 35292781, 2022). "GSDME-mediated is involved in the regulation of tumor immune microenvironment and antitumor immunity." (PMID 36457716, 2022). "In the present study, we show that PDAC tumour cells express GSDME at high levels to mediate resistance to pancreatic enzymatic digestion through a GSDME–YBX1–mucin pathway, thereby playing a tumour-promoting role beyond the known pore-forming function." (PMID 35292781, 2022). "For instance, GSDME activation suppresses tumor growth by increasing the antitumor properties of tumor-infiltrating NK cells and CD4+ and CD8+ T lymphocytes." (PMID 35844506, 2022). "GSDME, as a tumor suppressor, can improve the antitumor immunity by activation of pyroptosis, while inflammasome activation induced by pyroptosis further enhances the therapeutic efficacy of some immune checkpoint blockers." (PMID 36246400, 2022). "Chemotherapeutic agents activate Caspases to induce tumor cell death in either apoptosis or pyroptosis, depending on the expression level of GSDME in the cells." (PMID 35957895, 2022). "For example, the expression of GSDME in tumours is significantly lower than that in adjacent tissues." (PMID 35289335, 2022). "Latest studies reported that two other members of the GSDM family, GSDMB and GSDME, are cleaved by granzymes of killer lymphocytes to potentiate anti-tumor immunity via induction of tumor-cell pyroptosis." (PMID 36323669, 2022). "Based on these reports, GSDME is considered to be a tumour suppressor gene because GSDME inactivation inhibits its necrotic effects, thus promoting tumour formation." (PMID 35279675, 2022). "Existing studies have shown that chemotherapeutic drugs can induce caspase-3-mediated cleavage of GSDME, resulting in high GSDME expression and the formation of N-GSDME terminals, which lead to tumor cell pyroptosis." (PMID 36091790, 2022). "GSDME is also activated by granzyme-B delivered by cytotoxic lymphocytes into GSDME-positive tumours." (PMID 35455985, 2022). "Here we show that human PDAC tumour cells use gasdermin E (GSDME), a pore-forming protein, to mediate digestive resistance." (PMID 35292781, 2022). "CRIZO and ceritinib have been reported to induce tumour cell pyroptosis via the caspase‐3/GSDME‐dependent signalling pathway." (PMID 35855570, 2022). "Here, GSDME is considered a tumor suppressor by inducing pyroptosis and strengthening the anti-tumor effect." (PMID 36262473, 2022). "In tumor cell lines with high expression of GSDME, chemotherapeutic drugs like cycloheximide (CHX) can induce caspase-3 activation and cleavage of GSDME." (PMID 36497244, 2022). "A mouse xenograft model demonstrated that CVB3 significantly reduced tumor volume in vivo, and that this was accompanied by cleavage of casp-3 and GSDME." (PMID 36551691, 2022). "Lastly, we incorporate clinical data showing that GSDME (also named DFNA5) is overexpressed in tumor tissue of HNSCC patients, highlighting the relevance of this strategy." (PMID 35120582, 2022).
tumor (continued). "H&E staining of sectioned tumors showed that overexpression of GSDME significantly increased the area of inflammatory necrosis of the tumor after irradiation, and silencing of GSDME decreased the area." (PMID 36411454, 2022). "Studies have also demonstrated that the pyroptosis determinants DFNA5 and GSDME were lowly expressed in some tumor cells, making them less responsive to pyroptotic-induced cell death." (PMID 36611966, 2022). "Some chemotherapy drugs can switch caspase-3-mediated apoptosis to pyroptosis by cleaving GSDME into GSDME-N in GSDME-expressing tumor cells." (PMID 36246400, 2022). "In 2020, it was reported that granzyme B (GzmB) can activate pyroptosis by cleaving GSDME, which stimulates antitumor immune responses and further inhibits tumor growth." (PMID 36523974, 2022). "With the better understanding of the activation of GSDME, it has been found that the activation of GSDME can affect tumor therapy from both the efficacy and side effect aspects, which were illustrated in this section." (PMID 36612023, 2022). "For example, the tumor-suppressive effect of GSDME is mediated by tumor-infiltrating natural killer (NK) and CD8+T lymphocytes." (PMID 36003332, 2022). "GSDME facilitates the tumour cells to express mucin 1 and mucin 13, which form a barrier to prevent chymotrypsin-mediated destruction." (PMID 35292781, 2022). "In detail, IL-1β and IL-18 are released through the first activated Gzm B/caspase-3/GSDME pathway in target tumor cells, which later amplifies the inflammatory response by activating the caspase-1/GSDMD axis in MΦs." (PMID 36482419, 2022). "GSDME can be detected in the heart, brain, and tumor cells and has promising research prospects in tumor cells." (PMID 35647057, 2022). "Given that GSDME presents a tumor suppressive role, it has been reported that GSDME inactivation is a strategy developed by cancer cells to avoid cell death." (PMID 35120582, 2022). "GSDME expression in tumor cells can transform apoptosis into pyroptosis, which provides a way out of the poor efficacy of chemotherapy drugs and overcomes the drug resistance of tumor cells." (PMID 35647057, 2022). "Taking specific means to activate GSDME at tumor sites to enhance immune efficacy is a good antitumor strategy." (PMID 36612023, 2022). "Aside from caspases, granzyme A has been reported to cleave GSDMB in lymphocytes, and granzyme B was reported to directly cleave GSDME in tumor cells, ultimately contributing to tumor suppression by invoking pyroptosis." (PMID 36093182, 2022). "Reducing granzyme-induced pyroptosis through silencing of gasdermin E expression in cancer cells has been shown to contribute significantly to the escape of murine tumours from cytotoxic lymphocytes and accelerate tumour growth." (PMID 35401556, 2022). "Recently, it was suggested that GSDME is activated by chemotherapeutic drugs to stimulate pyroptosis of cancer cells and trigger anti-tumor immunity, which is identified as a tumor suppressor." (PMID 35462927, 2022). "In osteosarcoma, it has been demonstrated that Dioscin can inhibit tumor growth through GSDME-dependent pyroptosis." (PMID 36119049, 2022). "CAR T-cell therapy for cancer mainly induces caspase-3/GSDME-dependent tumour cell pyroptosis through the release of perforin and granzyme B." (PMID 35896522, 2022). "GSDME has also been shown to exert potentially tumor-suppressive effects in models of intestinal cancer." (PMID 36003332, 2022). "Given this, how to balance the role of GSDME in tumor therapy and therapeutic toxicity is a challenge to be addressed when designing anti-tumor therapy regimens targeting GSDME." (PMID 35462927, 2022). "Following cleavage by caspase-3, GSDME can induce tumour cell pyroptosis and enhance the antitumour immunity of T cells." (PMID 35292781, 2022).